PPARA (peroxisome proliferator activated receptor alpha)
Diseases named in the same sentence as PPARA in open-access papers (continued):
Sharing a sentence is not in itself a finding about the gene and the disease.
hyperlipidemia (continued). "The clinical approval of fenofibrate for treatment of hyperlipidemia offers a potential path for developing PPARα agonism for AD by repurposing this medication." (PMID 38828724, 2024). "Coffee-derived trigonelline, an alkaloid derivative of niacin (vitamin B3), alleviates hyperlipidemia by increasing PPARα and decreasing PPARγ expression." (PMID 38699583, 2024). "For instance, Kjellmaniella crassifolia-derived fucoidan ameliorates hyperlipidemia by improving PPARα-mediated fatty acid β-oxidation in Wistar rats." (PMID 38699583, 2024). "Dodecahexaenoic acid (DHA) ameliorates postprandial hyperlipidemia potentially by upregulating PPARα and the genes involved in fatty acid β-oxidation and down-regulating TG and ApoB secretion." (PMID 38699583, 2024). "Platelet PPARa critically mediates platelet activation and contributes to the prothrombotic status under hyperlipidemia." (PMID 38595995, 2024). "Glycosaminoglycans isolated from sea cucumber Holothuria leucospilota are found to ameliorate hyperlipidemia in male BALB/c mice by improving the expression of PPARα and ameliorating gut microbiota." (PMID 38699583, 2024). "The PPARα agonist OEA alleviates hyperlipidemia-mediated vascular calcification via triggering autophagy by activating PPARα." (PMID 36979952, 2023). "To exclude possible secondary effects of systemic hyperlipidemia in PPARα−/− mice and further substantiate that mitochondria function is regulated by PPARα in the corneal epithelium, we next used a genetic approach." (PMID 36943878, 2023). "PPAR agonists such as thiazolidinedione (targets PPARγ) and fibrates (targets PPARα) have been proven to improve insulin sensitivity and hyperlipidemia, respectively." (PMID 36830009, 2023). "Pharmacological targeting of PPARα with fenofibrate in pre-clinical models has demonstrated atherosclerotic plaque regression in the setting of hyperlipidemia." (PMID 35783870, 2022). "As a PPARα agonist, fenofibrate has been widely used for hyperlipidemia in clinics and can also promote fatty acid oxidation in the mitochondria and improve myocardial energy metabolism." (PMID 36291052, 2022). "The positive correlation between the extent of platelet reactivity and PPARα expression both in hyperlipidemic mice and patients with hyperlipidemia supports the role of PPARα in mediating platelet activation." (PMID 36232746, 2022). "Peroxisome proliferator-activated receptor alpha (PPARα) is a well-known drug against hyperlipidemia." (PMID 34502311, 2021). "Fenofibrate is an agonist drug for PPARα and is principally used for treatment of hyperlipidemia in spite of the presence of statins and several newer lipid-lowering agents." (PMID 34988225, 2021). "Fenofibrate is an agonist drug for peroxisome proliferator-activated receptor alpha (PPARα), used principally for treatment of hyperlipidemia." (PMID 34988225, 2021). "Pemafibrate, a novel selective PPARα modulator (SPPARMα), has been developed as a therapeutic agent against hyperlipidemia to reduce this side effect." (PMID 34502311, 2021). "The expression of PPARα was significantly downregulated in a hyperlipidemia group with tanshinone IIA treatment in rats." (PMID 34234682, 2021). "The expression of PPARα and ApoA-I was significantly downregulated in the hyperlipidemia group with tanshinone IIA treatment." (PMID 34234682, 2021). "Our previous experiments showed that AuCur inhibited the abnormal elevation of PPARα in hyperlipidemia and ameliorated other deleterious effects of lipid toxicity on the myocardium." (PMID 34765588, 2021). "Fenofibrate is an effective ligand for peroxisome proliferator-activated receptor alpha (PPARα) and has historically been used to regulate glucose and lipid metabolism in the treatment of different forms of hyperlipidemia and hypercholesterolemia." (PMID 34082742, 2021). "CREBH and PPARα synergistically activate the expression of PPARα target genes related to lipid metabolism, improving hyperlipidemia." (PMID 34579081, 2021).
hyperlipidemia (continued). "In this study, the mRNA and protein expression of PPARα in the hyperlipidemia-model rats induced by HFD were significantly reduced." (PMID 34681767, 2021). "Previous studies have presented the high efficiency of dual PPARα/γ agonists against hyperglycemia and hyperlipidemia." (PMID 34641558, 2021). "Fenofibrate, a peroxisome proliferator-activated receptor alpha (PPARα), is used as a drug to treat hyperlipidemia worldwide." (PMID 35010703, 2021). "In the three pathways, the targets SREBPs and PPARα are transcription regulators involved in hyperlipidemia-related lipid metabolism processes." (PMID 32435189, 2020). "FENO, a commercial drug of PPARα agonist, is usually used in the treatment of hyperlipidemia for its role in reducing TG and LDL and increasing HDL." (PMID 33132907, 2020). "Derivatives of N-acetyl-L-tyrosine were shown to have binding affinity to the peroxisome proliferator-activated receptor alpha (PPARα) at 50 μM (9.1 μg/mL), which is a regulator of lipid homeostasis, and PPARα agonists are described to decrease hyperlipidemia." (PMID 32013082, 2020). "It is known that PPARα, whose activation reduces hyperlipidemia, is highly expressed in intestinal epithelial cells." (PMID 31074378, 2019). "As a result, hepatic PPARα activation is associated with substantial triglyceride clearance and increased plasma HDL level, underpinning the clinical use of PPARα agonists to treat hyperlipidemia and cardiovascular disease (CVD)." (PMID 31614690, 2019). "The drug, bezafibrate, is a PPARa agonist used to treat hyperlipidemia and to prevent cardiovascular disease." (PMID 31358043, 2019). "Fibrate, a selective PPARα agonist, relieves hyperlipidaemia by promoting β-oxidation and induces a minor reduction in body weight." (PMID 30733541, 2019). "For instance, fibrates which are selective PPARα agonists, are often used in combination with statins to treat atherogenic hyperlipidemia and hypertriglyceridemia." (PMID 31614690, 2019). "The available selective synthetic ligands of PPARα, like fenofibrate, are efficient in pharmacotherapy of hyperlipidaemias by promoting fatty acid uptake, transport and oxidation." (PMID 30952952, 2019). "Fibrate drugs (including bezafibrate, clofibrate, fenofibrate, gemfibrozil, ronifibrate, etc.)are a class of classical PPARα agonists used to treat hyperlipidaemia and increase high-density lipoprotein cholesterol (HDL-c) in clinical settings." (PMID 29690611, 2018). "PPARα agonists are widely used to correct hyperlipidemia and were shown to reduce mortality and morbidity due to cardiovascular events." (PMID 29065888, 2017). "However, some clinical reports found the direct uptake of PPARα-enhancing drug, Fenofibrate (Downlip®, 200 mg, 1 tablet per day), for controlling hyperlipidemia may have side-effects in skin to cause photoallergen with basal vacuolation and superficial perivascular inflammation." (PMID 27210831, 2016). "Studies have shown that the sugar-free water extract of Shanzha was effective against hyperlipidemia by activating PPARα to lower lipid levels." (PMID 25110708, 2014). "These are classified as PPARα and PPARγ activators and are used in hyperlipidemia and hyperglycemia treatments." (PMID 24885009, 2014). "For example, OEA decreases food intake and lowers hyperlipidaemia in obese rats via PPARα activation and both OEA and PEA can stimulate insulin and GLP-1 secretion via activation of GPR119." (PMID 24593280, 2014). "On the other hand, activation of PPARα accelerates lipid absorption and increases fatty acid oxidation, leading to an improvement in lipid metabolism and a reduction of hyperlipidemia." (PMID 23762402, 2013). "Activation of peroxisome proliferator-activated receptor alpha (PPARα), on the other hand, increases fatty acid oxidation, leading to a reduction of hyperlipidemia." (PMID 23762402, 2013). "Hepatic PGC-1β overexpression reduces the beneficial effects of PPARα activation on gene expression, leading to hyperlipidemia." (PMID 22690247, 2012).
hyperlipidemia (continued). "Bezafibrate, a PPARα activator, is widely used to treat hyperlipidemia by reducing serum LDL, VLDL, and triglycerides." (PMID 22966221, 2012). "Whereas, PPARα agonists are clinically and functionally relevant as fibrate therapeutics against hyperlipidemia and agents for reducing the complications of peripheral vascular disease in diabetic patients." (PMID 23213319, 2012). "PPARα agonists are clinically and functionally relevant as fibrate therapeutics against hyperlipidemia and agents for reducing the complications of peripheral vascular disease in diabetic patients." (PMID 22675337, 2012). "Qualitatively, fasting-induced changes in gene expression resemble those induced by the fibrate class of drugs, which activate PPARα and promote fatty acid oxidation in white adipose tissue and are used clinically to treat hyperlipidemia." (PMID 22938590, 2012). "In clinical practice, PPARα agonists (fibrates) are used to treat hyperlipidemia, whereas PPARγ agonists (TZDs) are used to increase insulin sensitivity in muscle and adipose tissue." (PMID 20811644, 2010). "Naringenin ability to inhibit HMGR, the target of statins, while upregulating PPARα, the target of fibrates, suggest it can naturally find its place in the routine treatment of hyperlipidemia." (PMID 20811644, 2010). "Our data show that CAR activation modulates hepatic metabolism by lowering cholesterol and glucose levels, through effects on PPARα and adiponectin signaling pathways, and by compromising liver adaptations to hyperlipidemia." (PMID 19691840, 2009). "More importantly, up-regulation of the PPARα signaling pathway is also an adaptation of the liver to hyperlipidemia, and TCPOBOP disturbed this adaptation." (PMID 19691840, 2009). "Fibrates, members of peroxisome proliferators and agonists of PPARα, are used to treat hyperlipidemia by reducing plasma triglyceride and cholesterol levels via accelerating lipid metabolism." (PMID 17118139, 2006). "For example, fibrates targeting PPARα have been in use for hyperlipidemia therapy for years now." (PMID 40136698, 2025). "In addition, PPARα activation has been shown to alleviate hyperlipidemia-induced vascular calcification by suppressing autophagy-dependent ferroptosis triggered by mitochondrial DNA stress." (PMID 41438090, 2025). "PPARα is predominantly expressed in the liver, heart, and skeletal muscle, where it regulates fatty acid oxidation, ketogenesis, energy homeostasis, and lipid metabolism, offering protection against cardiovascular diseases and hyperlipidemia." (PMID 41200186, 2025). "Given PPARα’s roles in lipid metabolism, inflammation, and metabolic regulation, it presents a promising therapeutic target for treating metabolic disorders such as hyperlipidemia, MASLD, and CVDs." (PMID 40926269, 2025). "Similarly, Saccharina sculpera-derived fucoidans improve hyperlipidemia potentially by enhancing the gene expression of PPARα and PPARγ in Wistar rats." (PMID 38699583, 2024). "Betaine attenuates hyperlipidemia by activating PPARα and PPARγ and their downstream gene LXRα." (PMID 38699583, 2024). "Our results suggest that when a PPARα agonist is treated in animals with hyperlipidemia and fatty liver, pexophagy occurs in the liver due to peroxisome proliferation, which may result in residual peroxisomal processing." (PMID 39765694, 2024). "Global PPARα KO has been shown to result in systemic hyperlipidemia." (PMID 36943878, 2023). "Therefore, the role of PPARα in the development of renal diseases has recently been extensively studied, such as in mouse kidney tissues with hyperlipidemia and renal stone disease." (PMID 35222033, 2022). "Besides, Danhong injection significantly enhanced lipolysis and diminished fatty acids’ synthesis in the liver by increasing the mRNA transcription of PPARα in hyperlipidemia rats." (PMID 35528835, 2022).
hyperlipidemia (continued). "If pharmacological inhibition of PPARα or lipid droplet formation could be limited to intestines, this would serve as an option for reducing fat absorption and hyperlipidaemia, but also total caloric uptake." (PMID 34857752, 2021). "PPARα agonists can treat hyperlipidemia, whereas PPARγ agonists effectively manage type 2 diabetes." (PMID 34776958, 2021). "In the past, the fibrate drug for the treatment of hyperlipidemia is targeted at PPARα." (PMID 32577122, 2020). "Recently, a novel selective peroxisome proliferator-activated receptor alpha (PPARα) modulator (SPPARMα) pemafibrate (mw: 490.55 g/mol, Parmodia®, K-877, Kowa, Tokyo, Japan) was approved in Japan as a therapeutic agent against hyperlipidemia." (PMID 32872333, 2020). "And it is well known that the activation of the PPARα can reduces hyperlipidemia." (PMID 31572191, 2019). "Peroxisome proliferator-activated receptor α (PPARα) is a therapeutic target for hyperlipidemia." (PMID 30041488, 2018). "Our data suggested that MDG-1 was a PPARα agonist and a PPARγ antagonist; it could moderate the PPARs pathway, therefore ameliorating hyperlipidemia in HFD-fed mice." (PMID 28885549, 2017). "Hence, MDG-1, as a regulator of PPARα and PPARγ, possesses significant importance in a myriad of biochemical processes such as the regulation of blood lipid metabolism and hyperlipidemia." (PMID 28885549, 2017). "Also, a recent study demonstrated that DHA attenuates postprandial hyperlipidemia in a PPARα dependent manner by activation of fatty acid oxidation genes in the intestine leading to decreased TAG and apoB secretion." (PMID 24834104, 2014). "Geraniol activates both PPARγ and PPARα thereby improving hyperlipidemia and glucose uptake." (PMID 23176672, 2012). "Thus, targeting PPARα by the administration of pharmacological PPARα activators, e.g., fenofibrate, bezafibrate, gemfibrozil, is an effective approach for the treatment of hyperlipidemia." (PMID 22129452, 2011). "Although PPARα induction is beneficial in fasting and hyperlipidemia, effects of PPARα in diabetic nephropathy remain unclear." (PMID 21076544, 2010). "Therefore, the reduction of PPARα may lead to impaired clearance of cholesterol, leading to the initiation and development of hyperlipidemia." (PMID 36794015, 2023). "Considering that PPARα agonists fibrates, such as fenofibrates, have been widely used clinically to treat hyperlipidemia and, in some cases, NAFLD and NASH, it would be interestingly to further investigate whether fibrates also exert effects in the skeletal muscle." (PMID 35265044, 2022). "Since the adipose tissue is a large depot for free cholesterol, and PPARα is a drug target for treating hyperlipidemia and is well known to regulate lipid levels, we next wanted to determine whether adipocytic PPARα affects plasma cholesterol and lipoprotein levels." (PMID 35011564, 2021). "Therefore, PPARα is considered a potential therapeutic target for hyperlipidemia in NASH." (PMID 33671850, 2021). "Thus, PPARα is an potential therapeutic target for hyperlipidemia." (PMID 32472368, 2020). "The obtained results suggested that these three function foods can effectively improve liver lipid metabolism by normalizing the expressions of PPARα and HL, and protect liver from the oxidized trauma by enhancing hepatic function, which could be potentially used to remedy hyperlipidemia." (PMID 27146338, 2016). "Genes related to the PPAR pathway and lipid peroxidation were significantly (P < 0.05) upregulated (PPARγ) or downregulated (PPARα, CPT1A, ACOX1) in the liver of hyperlipidemia group." (PMID 41144456, 2025).
hyperlipidemia (continued). "PPAR agonists activate PPARA and/or PPARG receptors, improving inflammation, insulin sensitivity, hyperglycemia, and hyperlipidemia, which are the hallmarks of T2DM." (PMID 41011980, 2025). "The prediction outcomes from our network pharmacology analysis and molecular docking suggested that PPARα and AKT were pivotal targets in IXN against hyperlipidemia." (PMID 39619961, 2024). "Collectively, our results illustrated the impact of PPARα agonist (Fenofibrate) and AKT agonist (SC79) on hyperlipidemia." (PMID 39619961, 2024). "In summary, the activation of PPARα expression by PB and CA from WHB was important for the alleviation of hyperlipidemia and the structural adjustment of the gut microbiota." (PMID 38928784, 2024). "IXN activates AMPK/PPARα and PI3K/AKT signaling pathways, leading to reduction in lipid accumulation and oxidative stress, and ultimately ameliorating hyperlipidemia." (PMID 39619961, 2024). "Consistently, in patients with hyperlipidemia, the expression of ANGPTL3, APOA1, TG, and LDL is increased, while PPARα is decreased." (PMID 35755170, 2022). "Dealing with hyperlipidemia, fenofibrate decreased TNFα and IFN-γ, but the levels had increased in PPARα knockout mice." (PMID 33603777, 2021). "Compared with the NFD group, the PPARα protein and HMGCS1 protein of the hyperlipidemia rats induced by HFD decreased significantly, while the expression of the HMGCR protein increased significantly." (PMID 34681767, 2021). "Activation of LXR by TO901317 and PPARα by fenofibrate in combination improves glucose tolerance, alleviates insulin resistance, and blocks TO901317-induced hyperlipidaemia, but aggravates hepatic steatosis in high fat diet-induced obese mice." (PMID 29690611, 2018). "During fasting, dependency of ketogenesis on CREB3L3 is lesser extents than Ppara−/− mice suggesting importance of adipose PPARα for supply of FFA and hyperlipidemia in Creb3l3−/− mice." (PMID 27982131, 2016). "PPARα (K-877), PPARγ (INT131) and PPARα/δ (GFT505) modulators play pivotal roles in ABCA1 gene expression and apoA-I secretion, and increase HDL-C in patients with hyperlipidemia." (PMID 26225968, 2015). "Peroxisome proliferator-activated receptor-alpha (PPAR-α), a ligand-activated transcription factor, has emerged as a popular drug target for hyperlipidemia and inflammation in recent years." (PMID 24465540, 2014). "It has been known that pioglitazone affects lipid metabolism through action at PPARα, but the mechanism of action of JTXK granule on hyperlipidemia needs to be further studied." (PMID 25089145, 2014). "The notable increase in Pparα and decrease in Pparγ in the liver after CSE intervention suggests that CSE could reduce lipid accumulation in hyperlipidemia mice." (PMID 40077474, 2025). "The trends in the protein levels of FAS, LXR, SREBP1c, and PPARα were similar to those found in the mRNA expression, which is in accordance with a prior finding about the prevention of a probiotic-fermented rice buckwheat on HFD-induced hyperlipidemia in mice." (PMID 36230104, 2022). "- Anti-hyperlipidemia (↓plasma TG) in Western-diet fed C57BL6J and apoE2 mice but not in PPARα -deficient mice (100 mg/kg bw, p.o., 3 weeks)." (PMID 35769384, 2022). "Another research study found that EA stimulation of the “Fenglong” (ST 40) point contributed to increased expressions of ABCA1, PPARα, LXRα, and retinoid X receptor α messenger RNA, thus contributing to RCT, and somehow had a therapeutic effect on hyperlipidemia." (PMID 37675019, 2022). "It was reported that Kaempferol can increase lipid metabolism by increasing PPARα level, decreasing SREBPs level, and promoting expression of ACO and CYP4A1, so as to reduce visceral fat accumulation and improve hyperlipidemia in obese rats fed with high-fat diet." (PMID 34594388, 2021).